EGFR (epidermal growth factor receptor)
Diseases named in the same sentence as EGFR in open-access papers (continued):
Sharing a sentence is not in itself a finding about the gene and the disease.
breast carcinoma (continued). "To clarify the role of ERK1/2 in TGF‐β‐induced increase in EGFR expression, we pretreated the breast cancer cells with the ERK1/2 signaling inhibitor PD98059 and then stimulated these cells with TGF‐β." (PMID 29215776, 2018). "As an alternative cell survival pathway, STAT5a/b has a pro-tumor effect, via overexpression and activation, in head and neck squamous cell carcinomas, and EGFR has been shown to activate STAT5a/b in breast cancer cell lines." (PMID 29492209, 2018). "As such, expression of either EGFR or CK5/6 has been proposed for classification of basal-like breast cancer." (PMID 29409530, 2018). "The high expression of amphiregulin, a specific ligand of the EGFR, shows a highly significant correlation with cisplatin resistance in a variety of human breast cancer cell lines." (PMID 29940998, 2018). "β-catenin nuclear accumulation induced by Akt1 inhibition depended on the prolonged activation of EGFR signaling pathway in breast cancer cells." (PMID 30445978, 2018). "Studies characterizing macrophages co-invading with breast cancer cells showed higher expression of ErbB3, a member of the epidermal growth factor receptor (EGFR) family, in the invasive macrophages." (PMID 29636067, 2018). "Examples of this include the use of trastuzumab following HER2 testing in breast cancer, use of endocrine therapy in breast cancer and guiding EGFR targeted therapies in colorectal cancer using KRAS testing." (PMID 30234014, 2018). "In this study, we found that the EGFR expression was significantly lower in Smad3‐silenced breast cancer cells treated with MTM than in the cells with single‐silenced Smad3." (PMID 29215776, 2018). "EGFR-mediated β-catenin nuclear accumulation is critical for Akt1 inhibition-induced breast cancer metastasis." (PMID 30445978, 2018). "Further study indicated that MYOF acts as a key regulator in EGFR degradation after its activation and internalization in breast cancer cells." (PMID 30213946, 2018). "A greater understanding of mechanisms driving EGFR signaling in breast cancer is, therefore, warranted; in particular, how EGFR activity in this disease affects immunosuppressive pathways mediated by PD-L1." (PMID 30021161, 2018). "Breast cancer cells predominantly respond to EGFR agonists in a proliferative fashion supporting its role as an oncogene." (PMID 30250119, 2018). "As expected, the Smad3 knockdown markedly suppressed the TGF‐β‐triggered upregulation of the mRNA and protein expression of EGFR in two breast cancer cells." (PMID 29215776, 2018). "TGF‐β promotes the migration and invasion abilities of breast cancer cells, along with the increase in EGFR expression." (PMID 29215776, 2018). "miR-24 targets two regulators (tyrosine-protein phosphatase non-receptor type 9 (PTPN9) and receptor type tyrosine protein phosphatase F (PTPRF)) of EGFR activation, thereby promoting metastasis of breast cancer." (PMID 29455658, 2018). "In fact, the rapid ER signaling in breast cancer epithelium also requires the transactivation of EGFR and/or IGFR1." (PMID 29867480, 2018). "These included important oncogenic signaling proteins such as epidermal growth factor receptor, as well as the breast cancer stem cell marker CD44." (PMID 29892572, 2018). "The GPER-mediated transactivation of EGFR occurs via Gβγ-subunit signaling in breast cancer cells, following the same pathway as in other GPCRs." (PMID 29360846, 2018). "Retinoblastoma binding protein 2 (RBP2), an ER co-regulator is overexpressed in tamoxifen-resistant breast cancer patients and increases the stability of RTKs such as EGFR and HER2." (PMID 29455658, 2018). "Collectively, these results suggested the activation of EGFR mediates β-catenin nuclear accumulation in Akt1-impaired breast cancer cells." (PMID 30445978, 2018). "To the best of our knowledge, we disclosed for the first time that EGFR-mediated β-catenin nuclear accumulation is critical for the Akt1 inhibition-induced breast cancer metastasis." (PMID 30445978, 2018).
breast carcinoma (continued). "We have previously demonstrated via the WAP-TGFα transgenic mouse model that EGFR is colocalized with the oncogenic adaptor protein MUC1 in hyperplastic and tumor tissues and EGFR-driven breast cancer is largely MUC1-dependent." (PMID 29464085, 2018). "Consistently, knockdown of Smad3 in breast cancer cells also decreases the upregulated EGFR expression induced by TGF‐β treatment." (PMID 29215776, 2018). "TGF‐β promotes the migration and invasion abilities of breast cancer cells and increases the EGFR expression." (PMID 29215776, 2018). "Tamoxifen has been shown to act as a GPER agonist, and GPER has been implicated in tamoxifen resistance via its upregulation in a tamoxifen resistant breast cancer cell line which results in the activation of epidermal growth factor receptor (EGFR)." (PMID 29899833, 2018). "AKT is one of downstream targets of EGFR pathway and there is correlation between high levels of NF-kB activation and EGFR overexpression in breast cancer." (PMID 30618758, 2018). "Canonical Smad3 signaling and ERK/Sp1 signaling pathways are required for the TGF‐β‐induced upregulation of EGFR and the enhancement of migration and invasion abilities of breast cancer cells." (PMID 29215776, 2018). "Here, to explore the molecular mechanism by which miR-539 suppresses the progression of breast cancer, we identified EGFR as a direct target gene of miR-539." (PMID 29391441, 2018). "It was shown that the EGFR pathway activation promotes the formation of invadopodia in breast cancer cells, which increases their capacity to degrade the surrounding extracellular matrix." (PMID 29596308, 2018). "Those genes are the epidermal growth factor receptor (EGFR) and the breast cancer genes BRCA1 and BRCA2." (PMID 30546831, 2018). "Recently, the opposite role of decorin and versican in the regulation of the cross talk between estradiol receptor and EGFR/IGF-IR signaling pathways in estrogen-responsive breast cancers have been discussed." (PMID 29559954, 2018). "Our findings indicated a possible cooperation between TGF‐β and EGFR in enhancing breast cancer aggravation." (PMID 29215776, 2018). "Our recent studies demonstrate an enhanced localization of EGFR in the nucleus of metastatic breast cancer cells as compared to primary tumor cells." (PMID 30250119, 2018). "One such upregulated mediator of therapeutic resistance is the human epidermal growth factor receptor (HER) family member HER3, associated with poor prognosis in several epithelial malignancies including breast cancer." (PMID 30092835, 2018). "We have shown that ALIX is a negative regulator of EGFR activity, that its depletion significantly augments IFNγ-induced PD-L1 surface expression in human breast cancer cells, and that this upregulation is EGFR activity dependent." (PMID 30021161, 2018). "Most HER2-positive breast cancer cells also express EGFR and HER3, our finding suggest that any trastuzumab effects on these cells must be initiated through the interaction between trastuzumab and HER2." (PMID 29490608, 2018). "The combination of EGFR-TKIs and crizotinib was shown to have a more pronounced effect than a single drug regimen on breast cancer." (PMID 29455668, 2018). "In this study, we demonstrated that the expression of TGF‐β is positively correlated with the EGFR expression in breast cancer tissues, and the increased levels of TGF‐β and EGFR are associated with the poor prognosis of patients with cancer." (PMID 29215776, 2018). "Taken together, our results demonstrate that miR-539 functions as a tumor suppressor in breast cancer by downregulating EGFR, supporting the targeting of the novel miR-539/EGFR axis as a potentially effective therapeutic approach for breast cancer." (PMID 29391441, 2018). "In support of this report, we did find more co-localization of EGFR with the early endosomes marker EEA.1 in Akt1-impaired breast cancer cells." (PMID 30445978, 2018).
breast carcinoma (continued). "In breast cancer, Wnt3 over-expression activates Wnt/β-catenin pathway which leads to trans-activation of EGFR and promotes EMT in trastuzumab-resistant cells." (PMID 29986466, 2018). "In this study, the relationship between TGF‐β and EGFR expression in 67 breast cancer tissues was investigated through immunohistochemistry." (PMID 29215776, 2018). "Akt1 kinase activation after EGFR stimulation is a process that involves Ca2+/CaM interaction in breast cancer cell models." (PMID 28614631, 2018). "Here the authors show cetuximab-guided Avidin-Nucleic-Acid-Nanoassemblies to be superior to cetuximab-doxorubicin conjugate, and show its efficacy in KRAS mutant breast cancer, allowing for therapeutic expansion of anti-EGFR therapy." (PMID 30287819, 2018). "Ectopic over-expression of miR-539 suppressed breast cancer cell proliferation and migration via reducing EGFR expression." (PMID 29391441, 2018). "Taken together, these results indicate that EGFR is a direct, functional target of miR-539 in breast cancer." (PMID 29391441, 2018). "Canonical Smad3 signaling and ERK/Sp1 signaling pathways were also crucial for the TGF‐β‐induced upregulation of EGFR expression and the enhancement of migration and invasion abilities of breast cancer cells." (PMID 29215776, 2018). "AREG as a novel target for breast cancer therapy is attractive, potentially reducing the side effects of broad EGFR inhibition while targeting breast tumor growth that is driven by AREG." (PMID 30367629, 2018). "Our goal was to predict EGFR pathway activity in two RNA-Seq datasets: a breast cancer cell line panel and from breast carcinoma patients in TCGA." (PMID 30001694, 2018). "TGF‐β was positively expressed in 59.7% of breast cancer tissues (40/67), EGFR expression was upregulated in 37.3% of breast cancer tissues (25/67), and EGFR and TGF‐β were co‐expressed in 29.9% of breast cancer tissues (20/67)." (PMID 29215776, 2018). "A cross-cancer effect is found between breast cancer and lung adenocarcinoma with HER2, HER2_pY1248, and EGFR_pY1068 levels decrease and 4E-BP1 levels increase associated with FGFR1 amplification for both histological tumor types." (PMID 30442178, 2018). "Recent evidence implicates that EGFR, c-erbB2 and its encoding gene HER2/neu, can also regulate CXCR4 expression at the post-transcriptional level in breast cancer cells." (PMID 30564115, 2018). "The capture efficiencies were also estimated by use of breast cancer cell line expressing low-EGFR, MCF-720 as controls and were 0.08 for sc-120 and 0.07 for cetuximab." (PMID 30104638, 2018). "We observed that lapatinib, a small-molecule ErbB2/EGFR inhibitor used for treatment of ErbB2-positive breast cancer, strongly upregulates Irf6 in detached ErbB2-positive human breast cancer cells BT-474, AU-565, and HCC-1419." (PMID 30545388, 2018). "Among selected breast cancer cell lines, the highest response to free simvastatin was observed for cell lines that overexpress EGFR, MDA MB 231 and SKBR3." (PMID 30388834, 2018). "Among these molecules, copy number gain and overexpression of the 5′‐inositol lipid phosphatase synaptojanin 2 (SYNJ2) in breast cancer provides a paradigmatic example of sustained EGFR activation by altered trafficking pathways." (PMID 29124875, 2018). "Following this initial discovery, the Lin group demonstrated that the C3BM complex is also required for activation of NF-κB by HER2, an EGFR-related RTK that is overexpressed in a large fraction of breast cancers." (PMID 30158935, 2018). "Activation of EGFR/ErbB2 signaling in tamoxifen-resistant ER+ breast cancer cells induces highly aggressive stem cell phenotype in these cells." (PMID 29455658, 2018). "We here disclose a novel Akt1/PIKfyve/EGFR/β-catenin signaling pathway, which contributes to the metastasis of breast cancer." (PMID 30445978, 2018).
breast carcinoma (continued). "Our study proposed a novel mechanism by which TGF‐β transactivates EGFR signaling and favors the migration and invasion of breast cancer cells." (PMID 29215776, 2018). "The RTK family includes a number of growth factor-mediated receptors, such as IGF1R, EGFR, and ErbB2/Her2, that are reported to promote several hallmarks of breast cancer." (PMID 30214383, 2018). "Lapatinib, a dual tyrosine kinase inhibitor which interrupts the HER2/neu and EGFR pathways, was approved to be prescribed for breast cancer and other solid tumors by FDA in 2007." (PMID 29455646, 2018). "Alternatively, in ER− breast cancers, miR-7 overexpression has been considered as a potential therapeutic strategy to exploit miR-7-mediated suppression of EGFR and IGF1R, which are often overexpressed in triple-negative breast cancer (TNBC)." (PMID 30214383, 2018). "While high percentage of HER2-positive breast cancer cells also overexpress EGFR, approximately 50% of TNBC cells overexpress EGFR." (PMID 30241301, 2018). "These advances in breast cancer classification have led to the identification of three molecular markers: Estrogen Receptor (ER), Progesterone Receptor (PR), and Human Epidermal Growth Factor Receptor (HER2)." (PMID 29416802, 2018). "Previous studies had demonstrated that EGFR and ERBB2 amplification was associated with sensitivity to lapatinib, which has been licensed for the treatment of HER2+ breast cancer clinically." (PMID 30258362, 2018). "Most HER2-positive breast cancer cells also express either EGFR, HER3 or both, which makes it difficult to explain the observed effects of trastuzumab." (PMID 29490608, 2018). "Blocking ER-α36 expression or the activity of EGFR/HER-2 or their downstream signaling MAPK/ERK significantly increases cisplatin sensitivity in breast cancer cells." (PMID 29940998, 2018). "TGF-β signaling can also transactivate the epidermal growth factor receptor (EGFR) to promote breast cancer migration." (PMID 29903994, 2018). "To further extend our finding that the FOXO3a-BRD4-CDK6 axis promotes resistance of PI3K/AKT inhibition, we treated BT474 cells with Lapatinib (1 μM), which is an EGFR/HER2 dual tyrosine kinase inhibitor that is commonly used in breast cancer treatment." (PMID 30518851, 2018). "In pathological settings, mostly in lung and breast cancer and in glioblastoma, the EGFR is a driver of tumorigenesis." (PMID 29124875, 2018). "As the hetero-dimerization of HER2 and EGFR drives breast cancer progression and cancer stemness, we then observed the expression of CD44, HER2, and EGFR." (PMID 29464036, 2018). "The detailed mutual regulatory mechanisms of ER-α36 and EGFR/HER-2 in cispaltin resistance in breast cancer cells need further study." (PMID 29940998, 2018). "Amphiregulin (AREG), a ligand of EGFR, has been found to be overexpressed in estrogen receptor (ER)-positive breast cancer." (PMID 30367629, 2018). "Taken together, our data strengthen the link between the tumor microenvironment and suppression of the immune system in human breast cancers by shedding light on the signaling interplay between EGFR, ALIX, and PD-L1." (PMID 30021161, 2018). "Currently, treatment of breast cancer with receptor tyrosine kinase (RTK) inhibitors that target EGFR, such as gefitinib, has been met with mixed success." (PMID 30367629, 2018). "Our results provided the evidence that EGFR-mediated β-catenin nuclear accumulation is critical for the Akt1 inhibition-induced breast cancer metastasis." (PMID 30445978, 2018). "We have previously demonstrated that MUC1 promotes EGFR-dependent breast cancer by inhibiting the degradation of EGFR and promoting its trafficking to the nucleus." (PMID 29464085, 2018). "In invasive breast cancer, CTEN, associated with EGFR and HER2, contributed to the metastasis of breast cancer cells." (PMID 29985912, 2018). "The mRNA expression level of EGFR in two breast cancer cells was significantly increased after the TGF‐β treatment was administered." (PMID 29215776, 2018).
breast carcinoma (continued). "Results showed that exosomes targeting EGFR delivered let‐7a specifically to xenograft breast cancer cells, and GE11 peptide is likely superior to EGF for targeting EGFR‐expressing tumours." (PMID 29083099, 2018). "In previous studies, we tested different peptides to direct nanoparticles to different vascular biomarkers that represent various microenvironments of breast cancer, including αvβ3 integrin, P-selectin, EGFR, PTPμ, and fibronectin." (PMID 30335750, 2018). "The interaction of c-Src and PTPIP51 determines the sensitivity of Her2 amplified breast cancer cells towards EGFR-targeted TKIs." (PMID 30360441, 2018). "MED1 mediates induction of cell proliferation and migration and the genes associated with it (JUN, FOS, EGFR, VEGF, MMP1, and ERBB4) in breast cancer, which is abrogated when used together with miR-191-inhibition." (PMID 30087366, 2018). "On the other hand, FABP5 has been reported to enhance the metastatic potential and tumorigenesis through activation of EGFR signaling pathway in breast cancer and induce the epithelial-mesenchymal transaction (EMT) in hepatocellular cancer." (PMID 29914512, 2018). "To investigate the mechanism by which TGF‐β upregulates EGFR expression in breast cancer cells, we analyzed the EGFR promoter region using online bioinformatics tools." (PMID 29215776, 2018). "For instance, in breast cancer, miR-133a regulates the cell cycle and proliferation during tumorigenesis by targeting epidermal growth factor receptor (EGFR) through the downstream molecule Akt." (PMID 30174600, 2018). "Our study demonstrated that TGF‐β promotes the migration and invasion abilities of breast cancer cells through the upregulation of EGFR expression." (PMID 29215776, 2018). "This system was utilized to simultaneously detect two biomarkers, human epidermal growth factor receptor 2 and epidermal growth factor receptor, in a breast cancer orthotopic model." (PMID 29977484, 2018). "In EGFR‐silenced cells, TGF‐β fails to induce a more aggressive phenotype, and this result indicated that EGFR is required for the TGF‐β‐induced increase in the invasion ability of breast cancer cells." (PMID 29215776, 2018). "To extend our findings to other breast cancer models of EGFR signaling, we applied a similar EGF–trametinib treatment combination to our dox-inducible model of EGFR expression in the metastatic Ca1a cells." (PMID 30250119, 2018). "EGFR is well known as a treatment target for colorectal, head and neck, and non-small cell lung cancers, and is also a therapeutic target for breast cancer." (PMID 30347895, 2018). "In breast cancer cells, translocation of EGFR to mitochondria has been shown to occur upon EGF stimulation resulting in phosphorylation of the cytochrome c oxidase subunit II." (PMID 29124875, 2018). "Cumulative clinical data suggest aberrant HER1 (EGFR) and HER2 signalling is causally associated with increased cancer cell progression, shorter survival, and a poor outcome for patients with breast carcinomas." (PMID 29925812, 2018). "This diagram shows that UBASH3B is down-regulated by ER and cisplatin and can promote breast cancer progression through EGFR." (PMID 29492198, 2018). "Epidermal growth factor receptor (EGFR) in addition to VEGF is a target pathway of solid tumors including breast cancer, which is structurally related with erythroblastic leukemia viral oncogene (ErbB) family of proteins." (PMID 29342116, 2018). "In the last decades, a multitude of molecular abnormalities have been discovered representing potential druggable alterations, such as mutations of EGFR, ALK in NSCLC and HER2-mutations in breast cancer." (PMID 29881714, 2018). "Nonetheless, anti-EGFR therapy is less effective in breast cancer than in lung, colon, head, and neck cancers and there is therefore the need to fully understand the mechanisms underlying EGFR regulation to design novel targeted strategies." (PMID 29674627, 2018).